CLK2 (CDC like kinase 2)
Description:
Dual specificity kinase acting on both serine/threonine and tyrosine-containing substrates. Phosphorylates serine- and arginine-rich (SR) proteins of the spliceosomal complex. May be a constituent of a network of regulatory mechanisms that enable SR proteins to control RNA splicing and can cause redistribution of SR proteins from speckles to a diffuse nucleoplasmic distribution. Acts as a suppressor of hepatic gluconeogenesis and glucose output by repressing PPARGC1A transcriptional activity on gluconeogenic genes via its phosphorylation. Phosphorylates PPP2R5B thereby stimulating the assembly of PP2A phosphatase with the PPP2R5B-AKT1 complex leading to dephosphorylation of AKT1. Phosphorylates: PTPN1, SRSF1 and SRSF3. Regulates the alternative splicing of tissue factor (F3) pre-mRNA in endothelial cells. Phosphorylates PAGE4 at several serine and threonine residues and this phosphorylation attenuates the ability of PAGE4 to potentiate the transcriptional activator activity of JUN.
Tractability: Small molecule: a structure with a bound ligand is known; a high-quality ligand is known; it has a high-quality binding pocket; it belongs to a druggable protein family. PROTAC: a small molecule that binds it is known.
Target class: Protein Kinase; Enzyme; CMGC protein kinase group; Kinase; CMGC protein kinase CLK family
Chemical probes: MU1210 (high quality), PD134312, SGC-CLK-1 (high quality), T3-CLK (high quality)
Gene: Protein-coding gene on chromosome 1 (155,262,868 to 155,278,491, reverse strand). Ensembl gene ENSG00000176444.
Subcellular location: Nucleus; Nucleus (Isoform 1); Nucleus speckle; Nucleus speckle (Isoform 2)
Subcellular location (Human Protein Atlas): Nucleoplasm; Nuclear bodies
Gene Ontology:
Molecular function: identical protein binding; protein binding; protein serine/threonine kinase activity; protein tyrosine kinase activity; ATP binding; protein kinase activity; protein serine kinase activity; protein serine/threonine/tyrosine kinase activity
Biological process: protein phosphorylation; regulation of RNA splicing; response to ionizing radiation; negative regulation of gluconeogenesis; protein autophosphorylation
Cellular component: nuclear body; nuclear speck; nucleoplasm; nucleus
Genetic constraint (gnomAD): Loss-of-function variants: 12 observed, 71.26 expected, observed/expected ratio (o/e) 0.17, 90% interval 0.11 to 0.27. The upper end of that interval is the gene's LOEUF score, 0.27, which puts it in group 1 of 6, group 1 being the genes least tolerant of losing a copy. Missense variants: 500 observed, 682.56 expected, observed/expected ratio (o/e) 0.73, 90% interval 0.68 to 0.79. Synonymous variants: 223 observed, 231.75 expected, observed/expected ratio (o/e) 0.96, 90% interval 0.86 to 1.08.
Homologues: Orthologues: chimpanzee CLK2 (100% identical), guinea pig CLK2 (99% identical), rabbit CLK2 (99% identical), dog CLK2 (98% identical), pig CLK2 (98% identical), rat Clk2 (97% identical), mouse Clk2 (97% identical), macaque CLK2 (91% identical), tropical clawed frog clk2 (84% identical), zebrafish clk2a (78% identical), zebrafish clk2b (69% identical), Drosophila melanogaster Doa (62% identical), and 1 more. Paralogues in human: CLK3 (60% identical), CLK4 (55% identical), CLK1 (52% identical), DYRK1B (27% identical), DYRK1A (27% identical), HIPK3 (24% identical), HIPK1 (24% identical), HIPK2 (23% identical), DYRK4 (23% identical), DYRK3 (23% identical), DYRK2 (22% identical), HIPK4 (19% identical).
Diseases named in the same sentence as CLK2 in open-access papers:
CLK2 is named in the same sentence as 49 diseases in open-access papers, as found by Europe PMC text mining. Sharing a sentence is not in itself a finding about the gene and the disease. The quoted sentences say what the papers report.
breast carcinoma (23 papers, 2016 to 2025). "CLK play an essential role in MYC-driven tumors, and increased expression of CLK2 reduces the prognosis of MYC-amplified breast cancer patients." (PMID 40731028, 2025). "It has been reported that CLK2 is highly expressed in various solid tumors (such as breast cancer, lung cancer, esophageal squamous cell carcinoma, and colorectal cancer), and acts as an oncogene." (PMID 38617434, 2024). "In luminal breast cancer cells, CLK2 modulates the splicing of mRNAs in the EMT pathway to regulate tumor development." (PMID 38617434, 2024). "For example, several breast cancer cell lines have been found to display highly variable levels of CLK2 expression." (PMID 37131806, 2023). "CLK2 has previously been pharmacologically targeted in MYC-driven breast cancer and genetically in GBM." (PMID 35731869, 2022). "The targeting of CLK2 with the inhibitor T-025 in an allograft model of MYC-driven spontaneous breast cancer resulted in significant anti-tumour effects, including the induction of skipped exons, of apoptosis, and growth suppression." (PMID 33846420, 2021). "CLK2 also acts as an oncogene in breast cancer—it is amplified and overexpressed in a significant fraction of breast tumors and its downregulation inhibits breast cancer growth in cell culture as well as in xenograft models." (PMID 33066143, 2020). "RNA interference-mediated silencing experiments indicated that a member of CLKs, CLK2, promotes cell proliferation, migration and invasion of breast cancer cells, and the growth of tumor xenograft in mice." (PMID 32106418, 2020). "They report that a novel, orally administered CLK2 inhibitor (T‐025) induces exon skipping, which results in cancer cell growth reduction, especially in breast cancer (BCa) MYC‐driven tumors." (PMID 29789342, 2018). "Our study offers the CLK inhibitor as a novel therapeutic option for cancer patients, particularly for poor prognosis patients with MYC‐amplified and high CLK2‐expressing breast cancer." (PMID 29769258, 2018). "As oncogenic kinase CLK2 is involved in regulating alternative splicing and has been found overexpressed in breast cancer and glioblastoma." (PMID 27588394, 2016). "Cdc2‐like kinase 2 (CLK2), an oncogenic RNA‐splicing kinase pivotal in breast cancer, plays a significant role, particularly in the context of triple‐negative breast cancer (TNBC), a subtype marked by substantial medical challenges due to its low survival rates." (PMID 38723164, 2024). "Moreover, a dual CLK2/TKK inhibitor exhibited pronounced antiproliferative effects in various TNBC cell lines while exerting minimal impact on luminal breast cancer cells." (PMID 38723164, 2024). "These genes included NKX2–5, which is predicted to regulate aberrant gene expression in human MDS and CLK2, a proposed oncogene in breast cancer; the promoters of both of these genes were hypomethylated in 15-month-old tet2m/m fish compared with 15-month-old tet2wt/wt fish." (PMID 37937078, 2023). "The CLK2 gene has been identified as an oncogene in sporadic breast cancer." (PMID 35625741, 2022). "As a result, CLK2 inhibitors are developed in breast cancer and even other cancers." (PMID 35860803, 2022). "Moreover, a genome-wide association study (GWAS) of breast cancer declared identification of 65 novel loci associated remarkably with a high risk of breast cancer at P < 5 × 10− 8 such as FES, MAP 3 K11, CLK2, GRK7, USP25, DFFA, PKP1, and ZKSCAN3." (PMID 35650591, 2022). "CLK2 could serve as an oncogene in breast cancer, whereas downregulation of CLK2 could suppress tumor growth." (PMID 34420511, 2022). "Among three human LAMMER kinases, CLK2 has been cytogenetically mapped to a region incriminated in a high percentage of spontaneous cancers such as breast cancer, and analysis of breast and prostate tumor samples demonstrates aberrantly spliced CLK2 transcripts." (PMID 31275866, 2019).
breast carcinoma (continued). "Importantly, the increased expression of CLK2 worsens the survival of MYC‐amplified breast cancer patients, while having a slight effect on the survival of non‐MYC‐amplified breast cancer patients." (PMID 29769258, 2018). "Finally, breast cancer patients with both CLK2 high expression and MYC amplification showed poor prognosis in the clinical data." (PMID 29769258, 2018). "Considering the primary target of T‐025 as well as the oncogenic role of CLK2 in breast cancer, we hypothesized that cancer cells with higher CLK2 expression were dependent on the CLK2 kinase activity for their survival." (PMID 29769258, 2018). "As YAP hyperactivity has been characterized as essential in several human tumor types, including breast cancer, it follows that cancer cell lines with lower CLK2 activity may display increased aggressiveness by activating YAP through the splicing-based mechanism presented here." (PMID 38126343, 2023). "This may be a part of the mechanism by which CLK2 regulates breast cancer progression." (PMID 32106418, 2020). "Conversely, CLK2 was significantly overexpressed in breast tumor, TNBC, and luminal BC subtypes, which aligns with its role as an oncogenic kinase in breast cancer." (PMID 40731028, 2025). "CLK2 acts as an oncogene and promotes cell invasion and migration via AS of genes in EMT pathways in breast cancer." (PMID 35860803, 2022). "These clinical observations suggest that high expression of CLK2 and MYC amplification worsen the prognosis of particular subtypes of breast cancer patients and that CLK inhibitor would be more effective to these poor prognosis cancers." (PMID 29769258, 2018). "The oncogenetic kinase effect of CLK2 was reported previously in other cancer types such as breast cancer by regulating the mRNA splicing, however the protein level of CLK2 was not alter upon antioxidant treatment in MHCC97L." (PMID 34924003, 2021). "We observed that breast cancer cell lines with both amplified MYC and highly expressed CLK2 were significantly sensitive to other breast cancer cell lines (Fig EV5); however, we did not observe significant difference in cancer cell lines from other original organ types." (PMID 29769258, 2018). "We also observed that the splice factor kinase CLK3, but not CLK2 and CLK4, was also induced in hypoxic DU145 prostate, HT29 colon and MCF7 breast cancer cell lines." (PMID 29606096, 2018). "Further, although only amplified MYC did not significantly worsen the prognosis in breast cancer patients categorized as ER‐positive, HER2‐negative, and high‐proliferative subtype, patients with both high‐expressed CLK2 and MYC amplification showed significantly poor outcomes." (PMID 29769258, 2018).
glioblastoma (6 papers, 2016 to 2025). The most malignant astrocytic tumor (WHO grade IV). "In our study, CLK2 deficiency markedly decreased glioblastoma tumor volume at 4.5 weeks (GSC11) and 8.5 weeks (GSC272) after implantation in mice." (PMID 27050366, 2016). "Highly expressed CLK2 was associated with poor outcome in glioblastoma." (PMID 27050366, 2016). "Upregulated expression of CLK1 and CLK2 is negatively correlated with prognosis in patients with kidney tumors and glioblastoma/colorectal carcinoma, respectively." (PMID 37342192, 2023). "This study is the first to provide evidence of the function of CLK2 in the cell cycle in glioblastoma." (PMID 27050366, 2016). "In the present study, we examined newly discovered function of CLK2 in glioblastoma stem cells (GSCs) in vitro and in vivo." (PMID 27050366, 2016). "CLK2 is expressed in glioblastoma cells and human glioblatoma specimens, and knockdown of CLK2 expression not only enhances the survival of mice with glioblastoma but also decreases tumor growth." (PMID 27050366, 2016). "We also found that CLK2 is amplified and overexpressed in human glioblastomas and that its downregulation inhibits glioblastoma cell growth in cell culture models and glioblastoma tumorigenesis in a xenograft assay." (PMID 27050366, 2016). "We performed orthotopic mouse xenograft experiments to determine the effect of CLK2 expression on glioblastoma progression in vivo." (PMID 27050366, 2016). "Because of the CLK2-mediated effect on glioblastoma, we examined the expression of several proteins in the tumor xenografts from GSC272 and GSC11 cells." (PMID 27050366, 2016). "We observed moderate (grade 2) and strong (grade 3) staining for CLK2 in 28 (56%) and 16 (32%) glioblastoma samples, respectively." (PMID 27050366, 2016). "In two glioblastoma xenograft models, the survival duration of mice with CLK2-knockdown GSCs was significantly longer than mice with control tumors." (PMID 27050366, 2016). "CLK1 and CLK2 are upregulated in breast and colorectal carcinomas and glioblastoma." (PMID 37342192, 2023). "Furthermore, CLK2 acted a pivotal part in the control of cell cycle and prognosis of glioblastoma by regulating FOXO3a/p27 pathways." (PMID 34420511, 2022). "In glioblastoma, the CLK2 expression is elevated and correlated with poor survival." (PMID 35860803, 2022). "We report herein the identification of a function of CLK2 in glioblastoma stem cells." (PMID 27050366, 2016). "Studies elucidating a potential feedback loop between AKT and CLK2 in glioblastoma are needed." (PMID 27050366, 2016). "Furthermore, CLK2 regulates the cell cycle of glioblastoma cells via FOXO3/p27 signaling pathway." (PMID 35860803, 2022). "Knockdown of CLK2 expression in several GSC lines correlated with AKT/FOXO3a/p27 and arrest of the cell cycle at G1 and S phase in vitro and extended survival durations in orthotopic xenograft models of glioblastoma." (PMID 27050366, 2016). "In glioblastoma models, the combined inhibition of FGFR and reduced CLK2 expression synergistically induced apoptosis and cell cycle arrest, suggesting that pathways regulated by CLK2 may mediate resistance to single-agent FGFR inhibition." (PMID 41567627, 2025). "However, the function of CLK2 in glioblastoma progression has not been described." (PMID 27050366, 2016).
lung carcinoma (4 papers, 2016 to 2024). "Moreover, miR-573 suppressed CLK2 expression and interrupted the occurrence and development of lung cancer caused by CLK2 overexpression." (PMID 37029108, 2023). "In addition, we found that T‐025 showed high in vitro growth suppressive effect in an additional cancer cell line with higher CLK2 protein, that is, lung cancer NCI‐H1048; also, T‐025 caused moderate anti‐proliferative effect in normal fibroblast cell lines with lower CLK2 protein." (PMID 29769258, 2018). "The dual TTK/CLK2 inhibitor CC-671 provides a theoretical basis for overcoming ABCG2-mediated MDR in lung cancer patients." (PMID 38195567, 2024).
Alzheimer disease (3 papers, 2009 to 2025). A progressive, neurodegenerative disease characterized by loss of function and death of nerve cells in several areas of the brain leading to loss of cognitive function such as memory and language. "For example, aberrant CLK2 splicing is associated with exon 10 inclusion in tau, which produces the neurodegenerative fibrillar aggregates found in Alzheimer's disease." (PMID 19278650, 2009). "LAMTOR2 complex regulated focal adhesion dynamics during cell migration and CLK2 was proved to change in Alzheimer's disease." (PMID 28938616, 2017).
breast tumors (3 papers, 2017 to 2025). "In terms of the potential applications of T3 in disease, previous reports demonstrate that knockdown of CLK2 inhibits growth of breast tumors with overexpresseed CLK2 in cell and animal models of the disease, correlating with splicing alterations." (PMID 28232751, 2017).
colorectal cancer (3 papers, 2018 to 2023). A primary or metastatic malignant neoplasm that affects the colon or rectum. "Our study demonstrates that the elevated expression of CLK2 significantly correlates with local invasion, distal metastasis, and prognosis of patients with colorectal cancer." (PMID 35860803, 2022). "Real-time PCR and analyses of The Cancer Genome Atlas (TCGA) and Human Protein Atlas (HPA) database were utilized to evaluate the CLK2 gene transcription level and protein level of colorectal cancer (CRC) tissue." (PMID 35860803, 2022). "The study is aimed at exploring the potential roles of CLK2 in the development of colorectal cancer (CRC)." (PMID 35860803, 2022). "Our study suggests that CLK2 may be a potential prognostic biomarker and therapeutic target for colorectal cancer." (PMID 35860803, 2022). "The molecular mechanisms that CLK2 involved in colorectal cancer have rarely been reported." (PMID 35860803, 2022). "CLK2 might be a potential prognostic biomarker and therapeutic target for colorectal cancer." (PMID 35860803, 2022).
glioma (3 papers, 2022 to 2025). A benign or malignant brain and spinal cord tumor that arises from glial cells (astrocytes, oligodendrocytes, ependymal cells). "Our findings provide further insights into the potential role of CLK2 condensates in promoting IR for the maintenance of GSCs, a subset of cells that drives glioma progression." (PMID 39119950, 2024). "S5B), analysis of the GlioVis Chinese Glioma Genome Atlas (CGGA) dataset shows a significant association of higher expression of CLK2, but not CLK1, CLK3, or CLK4, with poor OS, and CLK2 mRNA expression significantly increases with grade in multiple brain cancers, including GBM." (PMID 35731869, 2022).
osteoarthritis (3 papers, 2023 to 2025). A noninflammatory degenerative joint disease occurring chiefly in older persons, characterized by degeneration of the articular cartilage, hypertrophy of bone at the margins and changes in the synovial membrane. "Currently, several CLK or CLK2 inhibitors are being investigated in clinical trials for their potential use in treating various conditions such as degenerative diseases, osteoarthritis, cancers, psoriasis, scleroderma, and tendinitis." (PMID 38723164, 2024).
prostate carcinoma (3 papers, 2014 to 2025). A carcinoma that arises from epithelial cells of the prostate gland. "HIPK1 treatment resulted in increased c-Jun dependent transcription activity in cell models of prostate cancer while CLK2 phosphorylation caused the opposite." (PMID 36671509, 2023).
colon cancer (2 papers, 2019 to 2020). "Based on our network, CLK2, INTS3, and XAB2 may function as oncoproteins because that the high expression of these SFs showed poor survival of colon cancer." (PMID 32962686, 2020).
Obesity (2 papers, 2021 to 2023). Accumulation of substantial excess body fat. "Diet-induced obesity and leptin receptor-deficient db/db mice lack CLK2 signal in the hypothalamic neurons." (PMID 37635967, 2023). "Thus, the current study suggests that CLK2 is a promising target in treating obesity associated with psychological disorders, at least in females." (PMID 37635967, 2023). "Through liver-specific CLK2 knockout mice, CLK2 regulates hepatic fat metabolism, fatty acid oxidation, and ketogenesis during fasting in diet-induced obesity (DIO) mice." (PMID 37635967, 2023). "Pharmacological inhibition and the knockdown of hypothalamic Clk2 led to obesity due to hyperphagia and lower energy expenditure." (PMID 37635967, 2023). "The underlying mechanisms of the reversed phenotype on obesity between CLK1 and CLK2 are unknown and will be further explored in future studies." (PMID 34526909, 2021). "Unlike the phenotype of the Clk1 knockout mice reported here, overexpression of CLK2 in the mediobasal thalamus can partially reverse the HFD-induced obese phenotype in mice, and mice lacking Clk2 in adipose tissue exhibited exacerbated obesity." (PMID 34526909, 2021).
psoriasis (2 papers, 2024). An autoimmune condition characterized by red, well-delineated plaques with silvery scales that are usually on the extensor surfaces and scalp. "The mRNA and protein levels of psoriasis markers were significantly increased in CLK2-deficient mice and mice that were intraperitoneally injected with TG003." (PMID 38724505, 2024). "Importantly, a CLK2 inhibitor promoted cytokine production, reduced viral replication, and accelerated murine psoriasis." (PMID 38724505, 2024).